ANGPT1 (angiopoietin 1)
Diseases named in the same sentence as ANGPT1 in open-access papers (continued):
Sharing a sentence is not in itself a finding about the gene and the disease.
infarction (4 papers, 2014 to 2021). A localised pathological necrosis of tissue resulting from obstruction of the blood supply usually by a thrombus, an embolus, or vascular torsion. "Vascular endothelial growth factor-B (VEGF-B) and angiopoietin 1 (ANGPT-1) are the main angiogenic factors that enhance endothelial cell proliferation and accelerate vascular growth in the infarction zone." (PMID 34204341, 2021). "Vascular endothelial growth factor-B (VEGF-B) and angiopoietin 1 (ANGPT-1), are the main angiogenic factors which enhance the proliferation of endothelial cells and speed the vascular regrowth within the infarction area." (PMID 30186566, 2018). "Similar to what was described for VEGF, genetically modified MSC expressing angiopoietin-1 were more effective in regenerating myocardial tissue after infarction than MSC alone." (PMID 24739658, 2014).
Nephropathy (4 papers, 2018 to 2026). A nonspecific term referring to disease or damage of the kidneys. "The ratio of circulating ANGPT2 to ANGPT1, has been shown to have prognostic value for the detection of kidney disease and heart failure." (PMID 39472324, 2024). "Animal studies indicate that treatment with angiopoietin-1 might reduce kidney damage in unilateral ureteral obstruction, streptozotocin-induced type-1 diabetes, and folic acid induced nephropathy." (PMID 29783932, 2018).
preeclampsia (4 papers, 2014 to 2023). Preeclampsia is a hypertensive disorder of pregnancy that is characterized by new-onset hypertension with proteinuria presenting after 20 weeks of gestation, and depending on mild or severe forms may initially present with severe headache, visual disturbances, and hyperreflexia. "Angiogenesis plays a role in gestational hypertension through upregulation of angiopoietin-1 (ANG-1) or activation of the renin angiotensin system (RAS) that causes high circulating levels of angiotensin-II (ANG-II)." (PMID 36900356, 2023). "We observed a decreased expression of angiopoietin-1 and angiomotin in IUGR-ECFCs, as reported in pregnancies complicated by preeclampsia with IUGR, in endothelial cells from knockdown angiomotin zebrafish, and also during the postnatal period in ECFCs from low-birth-weight newborns." (PMID 34576323, 2021).
primary congenital glaucoma (4 papers, 2019 to 2024). "We previously reported loss of function mutations in the receptor tyrosine kinase TEK or its ligand ANGPT1 cause primary congenital glaucoma in humans and mice due to failure of SC development." (PMID 31621585, 2019). "In the realm of whole exome sequencing, two additional genes associated with primary congenital glaucoma have been identified - TEK receptor tyrosine kinase/tyrosine kinase with immunoglobulin-like and EGF-like domains 2 (TEK/TIE2) on 9p21.2 and angiopoietin 1 (ANGPT1) on 8q23.1." (PMID 38435218, 2024).
vascular dementia (4 papers, 2022 to 2025). A degenerative vascular disorder affecting the brain. "The endothelial growth factor ANGPT-1 on the other hand, decreased neuroinflammation and improved cognition in an animal model of vascular dementia and has been shown to help maintain BBB integrity and stabilization of the neurovascular function." (PMID 40875171, 2025).
bladder cancer (3 papers, 2016 to 2022). "The TF-protein JUN (a regulator of ANGPT1, HPGD, ATF6B and OAS3) is associated with bladder cancer disease." (PMID 35617355, 2022). "In addition, the high expression of ANGPT1, bFGF, MMP-9, and Tie-2 has been reported as an important prognostic factor for the high-risk group of bladder cancer patients." (PMID 36428758, 2022). "Consistent with previous studies, we also found that AnxA2 knockdown significantly inhibited bladder cancer cell proliferation, migration, and invasion, along with remarkably decreased expression of proangiogenic proteins such as PDGF-BB, ANGPT1, ANGPT2, Tie-2, bFGF, GRO, IL-6, IL-8, and MMP-9." (PMID 36428758, 2022). "In addition, the downregulation of AnxA2 cells significantly inhibited the proliferation, migration, and invasion in bladder cancer along with the reduction in proangiogenic factors and cytokines such as PDGF-BB, ANGPT1, ANGPT2, Tie-2, bFGF, GRO, IL-6, IL-8, and MMP-9." (PMID 36428758, 2022).
brain injury (3 papers, 2014 to 2023). Acute and chronic (see also brain INJURIES, CHRONIC) injuries to the brain, including the cerebral hemispheres, CEREBELLUM, and brain STEM. "Plasma sST2 also correlated with an elevated angiopoietin-2/angiopoietin-1 ratio, which has been seen in and is thought to contribute to sequelae from traumatic brain injury." (PMID 35800259, 2022).
colitis (3 papers, 2018 to 2022). Inflammation of the colon. "In our previous study, we reported that COMP-angiopoietin-1 reduces the expression of VEGF-C and -D mRNA in colitis." (PMID 33138094, 2020).
diabetic kidney disease (3 papers, 2016 to 2022). Progressive kidney disorder caused by vascular damage to the glomerular capillaries, in patients with diabetes mellitus. "Inversely, ANGPT1 has exerted a protective effect against renal function decline and reduced level of ANGPT1 was detected in early diabetic kidney disease." (PMID 36506068, 2022).
endometriosis (3 papers, 2023 to 2025). The growth of functional endometrial tissue in anatomic sites outside the uterine body. "The novelty of this study was the finding of the combination of VCAM-1, VEGF, sICAM-3, angiopoietin-1, and sTie-2 protein changes, which have not been reported in UI at any time but rather individually in endometriosis, a condition that has been associated with UI." (PMID 40650261, 2025). "Additionally, estrogens and hypoxia-related factors [angiogenin (ANG), angiopoietin 1 (ANGPT1), or vascular endothelial growth factor (VEGF)] have been suggested to promote endometriosis-related EMT via MAPK/ERK, PI3K/AKT, or β-catenin cascades." (PMID 38674005, 2024).
hemorrhage (3 papers, 2017 to 2023). Loss of blood from the vascular compartment to the exterior or into nonvascular body space as a result of rupture or severance of the blood vessels. "Furthermore, in patients with aneurysmal subarachnoid hemorrhage, higher serum levels of ANGPT-1 at 72 h after hemorrhage were associated with a good outcome." (PMID 37569462, 2023). "Zhou and his colleagues reported that EA at ST36 acupoint improved neurological function recovery by upregulating angiopoietin 1 and 2 expression in the injured cortex of cerebral hemorrhagic rat." (PMID 28848607, 2017). "We found some evidence of associations between ANGPT1 methylation and patient recovery at 3 and 12 months post hemorrhage, although this does not replicate in the follow-up cohort (where we cannot adjust for surrogate variables)." (PMID 35359917, 2021).
Hyperglycemia (3 papers, 2019 to 2025). An increased concentration of glucose in the blood. "At 1 h post-hypoglycemia, the changes in ANGPT1, DKK1, and BOC had resolved, with no additional protein biomarker changes despite rebound hyperglycemia from 1.8 ± 0.1 to 12.2 ± 2.0 mmol/L." (PMID 38927344, 2024).
liver cancer (3 papers, 2021 to 2023). An epithelial or non-epithelial malignant neoplasm that arises from the liver. "Again, ANGPT2 (angiopoietin-2) as a prognostic marker plays a pivotal role in liver cancer and concomitantly with ANGPT1 (angiopoietin-1) and VEGF (vascular endothelial growth factor) promoted activity hypervascularity." (PMID 35163556, 2022).
lung carcinoma (3 papers, 2020 to 2021). "Alterations in the intron region of ANGPT1 were found in lung cancer and affected the expression level of ANGPT1, which lead to the neoplastic progression of lung cancer." (PMID 34039311, 2021). "Evidence has shown that lung cancer patients with a higher level of ANGPT1 had better survival, indicating that ANGPT1 is a prognostic marker for lung cancer, especially for predicting postoperative survival and recurrence." (PMID 34039311, 2021). "Furthermore, a recent study demonstrated that ANGPT1 could be a potential tumor suppressor gene for lung cancer." (PMID 34039311, 2021).
neuropathy (3 papers, 2012 to 2022). A disorder affecting the nervous system that manifests with pain, tingling, numbness, and/or muscle weakness. "In a mouse model of diabetic peripheral neuropathy, angiopoietin-1 promoted angiogenesis, suppressed inflammation, and induced signs of regeneration in sciatic nerves, pointing angiopoietin-1 as a new treatment option to improve neuropathy." (PMID 29535781, 2018). "Furthermore, Angpt1 expression levels, which were reduced in the presence of bone marrow neuropathy, were also lower in 6OHDA-lpr mice." (PMID 35466994, 2022).
osteosarcoma (3 papers, 2012 to 2024). A usually aggressive malignant bone-forming mesenchymal neoplasm, predominantly affecting adolescents and young adults. "Other stem cell markers such as STAT3 and Sox4 were also strongly expressed in MSCs, while angiopoietin-1 was highly expressed in osteosarcoma cells." (PMID 22852096, 2012). "Several of these genes have been studied in osteosarcoma including ANGPT1 upregulation associated with nonmetastatic disease and CGREF1 overexpression linked to a poor prognosis." (PMID 39701601, 2024). "In accordance with the results from the PCR the quantity of angiogenesis relevant factors including VEGF, ANGPT-1, ANGPT-2 and SDF-1 involved in cell recruitment and osteosarcoma progression in supernatant was measured by ELISA to gain insight on the effects of fucoidan on the protein level." (PMID 28632184, 2017).
type 2 diabetes (3 papers, 2015 to 2024). "The serum levels of Angiopoietin-like proteins (ANGPTL) 3, ANGPTL4, betatrophin, angiopoietin 1 and 2 were measured in 50 type 2 diabetic patients and 67 DN patients compared to 117 healthy participants." (PMID 39030467, 2024). "Studies have found that the circulating Angpt-2 level in patients with type 2 diabetes is increased, but the increase in Angpt1 is not obvious, which results in a significant increase in the Angpt-2/Angpt-1 ratio." (PMID 39082686, 2024).
Venous malformation (3 papers, 2018 to 2025). A vascular malformation resulting from a developmental error of venous tissue composed of dysmorphic channels lined by flattened endothelium and exhibiting slow turnover. "MAP3K3 is an enzyme downstream of the angiopoietin 1 and tunica internal endothelial cell kinase pathway; alterations in the tunica internal endothelial cell kinase pathway are associated with venous malformations." (PMID 40948689, 2025).
acute pancreatitis (2 papers, 2016 to 2020). An acute inflammatory process that leads to necrosis of the pancreatic parenchyma. "Studies have reported that ANGPT1 gene-modified human MSCs could promote angiogenesis and reduce acute pancreatitis in rats, while PDGFRA+ MSCs have enhanced skin repair/regeneration potential." (PMID 32252818, 2020). "Others showed that in some disease model like acute pancreatitis, the increase of the ANGPT1 could reduce the symptom by increasing the angiogenesis." (PMID 26901069, 2016).
acute respiratory distress syndrome (2 papers, 2019 to 2020). Progressive and life-threatening pulmonary distress in the absence of an underlying pulmonary condition, usually following major trauma or surgery. "Additionally, several animal models of acute respiratory distress syndrome (ARDS) have been successfully treated with MSCs or fibroblasts modified to express angiopoietin 1, a protein that antagonizes vascular inflammation observed in ARDS." (PMID 32764348, 2020).
asthma (2 papers, 2016 to 2021). "In an earlier study Angiopoietin-2 rather than Angiopoietin-1 was associated with asthma and Angiopoietin-1/Angiopoietin-2 ratio was positively correlated with lung function in adult asthma patients." (PMID 26937244, 2016). "Interestingly, Angiopoietin-1 and Angiopoietin-2 levels were recently detected to be upregulated in the induced sputum from patients with optimally treated asthma, and seemed to be also related to the smoking status." (PMID 26937244, 2016). "The MSC-pANGPT1 (angiopoietin 1 gene) were aerosolized in a rabbit OVA-induced asthma and reduced the expression of pro-inflammatory cytokine genes (IL-4, TNF, TGF-β, and MMP-9), which can be an additional beneficial effect in asthma treatment." (PMID 33959015, 2021). "Other proangiogenic factors VEGF, Angiopoietin-1 and osteopontin did not correlate with asthma severity or severity serum markers." (PMID 26937244, 2016). "Patients with asthma, regardless of the diseases severity had on average almost threefold higher mean Angiopoietin-2 serum levels and significantly increased Angiopoietin-1 and VEGF serum concentrations, reflecting probably ongoing angiogenesis in the airways." (PMID 26937244, 2016). "Serum concentrations of Angiopoietin-2, VEGF, Angiopoietin-1 and osteopontin did not correlate with classical markers of asthma severity or asthmatic inflammation: blood eosinophil number and serum ECP or total IgE levels." (PMID 26937244, 2016).
autoimmune disease (2 papers, 2012 to 2021). A disorder resulting from loss of function or tissue destruction of an organ or multiple organs, arising from humoral or cellular immune responses of the individual to their own tissue constituents. "SNPs in ANGPT1 gene have been associated with the risk of diseases such as autoimmune diseases, juvenile idiopathic arthritis, and portopulmonary hypertension." (PMID 22496856, 2012).
bacteremia (2 papers, 2021 to 2025). "Finally, others have compared univariate models with the MASCC for single outcome measures and found them superior to the MASCC, including for PCT and bacteremia, PCT and mortality, and angiopoietin-12/angiopoietin-1 ratio for predicting septic shock." (PMID 40467900, 2025).
brain cancer (2 papers, 2011 to 2024). A primary or metastatic malignant neoplasm affecting the brain. "ANGPT1 and ANGPT2 contribute to the glucose metabolism by interacting with VEGF and they are both indicated to have a prognostic value in adult forms of malignant brain tumors." (PMID 21726470, 2011).
cardiac hypertrophy (2 papers, 2013 to 2016). "Although we found the significant association of Angpt2 with cardiac hypertrophy and correlation between Angpt1 and LAD, the p-values for trend seemed to be low." (PMID 27991547, 2016). "Thus, angiopoietin 1 or 2 may play an important role in the development of glomerular hypertrophy after uninephrectomy." (PMID 24367525, 2013).
Cirrhosis (2 papers, 2013 to 2024). A chronic disorder of the liver in which liver tissue becomes scarred and is partially replaced by regenerative nodules and fibrotic tissue resulting in loss of liver function. "Messenger RNA (mRNA) expression levels of the angiopoietin genes (ANGPT1 and ANGPT2) involved in vessel maturation are altered, with the ANGPT1/ANGPT2 ratio increased compared with normal liver, cirrhosis, and other liver tumors." (PMID 23691331, 2013).
coronary artery disease (2 papers, 2020 to 2022). "The expression of the platelet-derived growth factor (PDGF), angiopoietin-1 (Ang-1) in patients with coronary artery disease of different studies was inconsistent." (PMID 32963822, 2020).
endometrial cancer (2 papers, 2003 to 2014). Primary or metastatic malignant neoplasm involving the endometrium (mucous membrane that lines the endometrial cavity). "Angiopoietin-1 and Ang-2 are previously unreported in endometrial cancer." (PMID 12942123, 2003). "Furthermore, the association between the expression of HIF-1α, increasing level of angiopoietin-1/angiopoietin-2, and enhanced synthesis of IL-8 was documented, also confirming the role of HIF-1α in the angiogenesis of endometrial cancer." (PMID 24745019, 2014).
hematoma (2 papers, 2022 to 2023). A hematoma is a collection of blood from a vascular structure into an extravascular space. "Contrarily, secretion of VEGFR2/3 receptor, Angpt1 and 2, and their receptor Tie2 was reduced in smokers’ hematomas." (PMID 35621464, 2022). "Results of main influencing factors PDGF-BB, VEGFA, Angpt1, MMP9, and GM-CSF were additionally confirmed by gene expression analysis, whereas except for GM-CSF all genes were expressed less in the smokers’ hematomas." (PMID 35621464, 2022). "Surprisingly secretion of VEGF-A, VEGF-D, and Leptin was increased in the smokers’ hematomas, but VEGFR2/3, Angiopoietin 1/2 (Angpt1/2), and its receptor Tie2 were decreased drastically." (PMID 35621464, 2022). "Regarding the Angpt/Tie2 axis, smoking conditions reduced the expression of Angpt1 in the hematomas, which could be restored to the non-smoker levels via GE stimulation." (PMID 37569229, 2023).
Hypoglycemia (2 papers, 2024 to 2026). A decreased concentration of glucose in the blood. "At the point of hypoglycemia, levels of ANGPT1 increased, while sTie-2 levels decreased, indicating enhanced protective effects in both groups, which then resolved." (PMID 41596469, 2026). "Under hypoglycemia, decreases in cadherin-5 and soluble angiopoietin-1 receptor (sTie-2) were observed, with increased P-selectin, intercellular adhesion molecule-3 (ICAM3), ANGPT1 and PAI-1." (PMID 41596469, 2026). "In the combined cohort, upon induction of hypoglycemia, there were significant decreases in cadherin-5 (p = 0.01) and sTie-2 (p = 0.01) and significant increases in P-selectin (p < 0.01), PAI-1 (p < 0.001), ANGPT1 (p < 0.001) and ICAM3 (p = 0.03) compared to baseline." (PMID 41596469, 2026). "With severe hypoglycemia, the study controls showed an increase in Angiopoietin 1 (ANGPT1) (p < 0.01) and Dickkopf-1 (DKK1) (p < 0.01), but no changes were seen with mild hypoglycemia." (PMID 38927344, 2024).
limb ischemia (2 papers, 2013 to 2019). A ischemia that involves the limb. "In a limb ischemia model, Angpt1-mediated Phd2 repression can switch Tie2 receptor-bearing macrophages to the pro-arteriogenic M2-like phenotype." (PMID 30760202, 2019).
lung adenocarcinoma (2 papers, 2021 to 2024). A carcinoma that arises from the lung and is characterized by the presence of malignant glandular epithelial cells. "Our bioinformatic analysis identified six downregulated DEGs (EDNRB, RXFP1, P2RY1, CALCRL, TEK, and ANGPT1) between lung adenocarcinoma and normal lung tissues based on two different microarray datasets." (PMID 34039311, 2021).
lung disease (2 papers, 2021). "There was some evidence that EDNRB, RXFP1, ANGPT1, and TEK are closely related to lung diseases and cancer." (PMID 34039311, 2021). "The present review focuses on the clinical impact of the Angiopoietin-1, Angiopoietin-2, and Angiopoietin-4 levels in patients diagnosed with NSCLC, emphasizing the interaction between them, and how they affect the development, progression, and metastasis of lung disease." (PMID 34833409, 2021).
lymph node metastasis (2 papers, 2022 to 2023). "When we evaluated the correlations between genetic alternations and clinicopathological findings, rs3739390 in ANGPT1 was associated with the presence of lymph node metastasis (p = 0.053)." (PMID 37120792, 2023). "Multiple logistic regression analysis showed association of urine exosomal TIMP (adjusted odds ratio (aOR): 3.09, 95% confidence interval (CI): 0.99–9.6, p = 0.052), angiopoietin-1 (aOR: 2.24, 95% CI: 0.97–5.15, p = 0.058) with lymph node metastasis." (PMID 36672532, 2022). "Regression model analysis showed border associations between U-Ex angiopoietin-1, TIMP concentrations, and lymph node metastasis." (PMID 36672532, 2022). "However, UEx Angiopoietin-1 (aOR: 3.09, 95% CI: 0.99–9.60, p = 0.052) and UEx TIMP (aOR: 2.24, 95% CI: 0.97–5.15, p = 0.058) have borderline significant positive effects on lymph node metastasis after adjusting for I-131 treatment (Yes/No) correction." (PMID 36672532, 2022).